TNF (tumor necrosis factor)
Diseases named in the same sentence as TNF in open-access papers (continued):
Sharing a sentence is not in itself a finding about the gene and the disease.
septic arthritis (26 papers, 2012 to 2025). "Anti-TNF therapy used in rheumatoid arthritis is associated with increased risk of septic arthritis." (PMID 35942056, 2022). "We have previously shown that anti-TNF treatment deteriorates host bacterial clearance in a murine model for hematogenous S. aureus septic arthritis, resulting in more-severe weight loss and kidney abscesses." (PMID 28264025, 2017). "BSRBR reported that the risk of septic arthritis with specific anti-TNF were etanercept HR 2.3 (CI = 1.2-4.4), infliximab HR 1.6 (CI = 0.8-3.2), and adalimumab HR 1.8 (CI = 1.0-3.5)." (PMID 26425605, 2014). "Interestingly, several opportunistic species that seldom cause septic arthritis were reported in the patients treated with anti-TNF therapy." (PMID 35942056, 2022). "Thus, it appears that CD4+ T cells are pathogenic during S. aureus septic arthritis due to their ability to produce proinflammatory cytokines such as TNF-α and IFN-γ via activated macrophages." (PMID 33546401, 2021). "This phenomenon appears to be associated with an elevated bacterial burden in the blood and kidneys, along with reduced systemic levels of TNF-α and IL-6, resulting in higher mortality in mice with hematogenous S. aureus septic arthritis." (PMID 40067374, 2025). "TNF-α, IL-1β, and IL-6 have been indicated as being the main cytokines that lead to severe inflammation that precedes cartilage and bone destruction in septic arthritis." (PMID 40005560, 2025). "Given the pivotal role of TNF in septic arthritis development, we evaluated the combination of antibiotics and TNF inhibitors using our hematogenous model." (PMID 38410388, 2024). "Sera collected at the end of the first septic arthritis experiment was analyzed for levels of IL-6, TNF-α, IFN-γ, MCP-1 and RANKL by ELISA." (PMID 32616791, 2020). "TNF-α and IL-1, released by monocytes/macrophages, are known to play a crucial role in septic arthritis." (PMID 31226163, 2019). "Synovial concentrations of the proinflammatory markers TNFα, IL-1β, and IL-6 are elevated in the course of disease, in which TNFα was a better indicator to discriminate bacterial arthritis from other inflammatory arthritis." (PMID 27688601, 2016). "BSRBR data showed that patients on anti-TNF therapy were twice as likely to develop septic arthritis as controls (adjusted hazard ratio [HR] = 2.0, 95% confidence interval [CI] = 1.2-3.7)." (PMID 26425605, 2014). "Importantly, our later study demonstrated that antibiotics combined with TNF inhibitor (enteracept) indeed is superior than antibiotics alone in treatment of septic arthritis in our mouse models." (PMID 38410388, 2024). "In horses with naturally occurring and experimentally induced OA and septic arthritis, increased levels of inflammatory components, such as leukocytes, interleukin (IL)-1β, IL-6, tumor necrosis factor α (TNF-α), and matrix metalloproteinases, has been demonstrated." (PMID 36937015, 2023). "Moreover, injection site reactions and septic arthritis secondary to IA TNF inhibitors have been experienced." (PMID 26451269, 2015). "Recently, we demonstrated that both anti-TNF and CLTA4 Ig pre-treatment aggravated S. aureus systemic infection with different clinical manifestations in a mouse model of S. aureus septic arthritis." (PMID 28264025, 2017). "This shows superior therapeutic efficacy of BM-MSC1, in treating septic arthritis in aged murine models, demonstrating excellent anti-inflammatory and regenerative capabilities through significant modulation of markers such as IL-10, VEGF, and TNF-α." (PMID 41296765, 2025). "During septic arthritis pathogenesis, macrophages secrete transforming growth factor-beta (TGF-β), IL-6, TNF-α, and IL-1β, cytokines with significant roles in NF-κB activation and osteoclast differentiation, perpetuating the inflammatory milieu and bone resorption." (PMID 40005560, 2025). "Mice lacking both TNFα and β demonstrated less severe S. aureus septic arthritis, yet exhibited increased mortality rates." (PMID 38410388, 2024).
septic arthritis (continued). "Anti-TNF therapy increased the bacterial load in kidneys but had no impact on septic arthritis development." (PMID 33546401, 2021). "Moreover, after depleting monocytes with etoposide, lower levels of TNF-α, IL-1β, O2−, H2O2, NO, metalloproteinase-2 (MMP-2), RANKL, and osteoprotegerin were detected, attenuating S. aureus-induced tissue destruction during septic arthritis in mice." (PMID 40005560, 2025). "Test findings such as TNF-alpha < 10, percent neutrophils < 80, blood procalcitonin < 0.39, synovial calprotectin < 52 mg/L, and neutrophil count < 15,000 all have a negative likelihood ratio < 0.1 and can help to rule out the diagnosis of septic arthritis." (PMID 33423115, 2021).
uremia (26 papers, 2015 to 2025). A clinical syndrome associated with the retention of renal waste products or uremic toxins in the blood. "Uremia is also associated with depletion of the plasmacytoid dendritic cell subset, and the hemodialysis procedure significantly impairs the ability to produce tumor necrosis factor-α (TNF-α) in response to LPS." (PMID 37524304, 2023). "We employed specific inhibitors of either IL-1, TNF-α or FGF in a cell culture system with serum from dialysis patients to assess their relative contribution to uremia associated malfunctioning of MSC and to establish potential therapeutic targets based on their functional importance." (PMID 30108259, 2018). "The synthesis and secretion of TNF-α in monocytes, furthermore accelerate vascular calcification in uremia." (PMID 37364352, 2023). "We further examined the potential contribution of TNF and uremia on cTNFR1/2 elevations and the relationship of cTNFR1/2 with sustained kidney injury after AKI and with progression to fibrosis (AKI-to-CKD)." (PMID 37759437, 2023). "Recent data have shown that lipopolysaccharides, TNF-α, and IL-1 present in uremia stimulate leptin expression by signaling through the central melanocortin system." (PMID 34835927, 2021). "Multiple experts emphasized TNF signaling as central element within the altered cytokine network of uremia-induced EC dysfunction." (PMID 34858433, 2021). "Uremic toxins from BiNx serum amplified the expression of iNOS, IL-1β, and TNF-α, supporting uremia-induced proinflammatory macrophages." (PMID 33436518, 2021). "As previously noted, high IL‐10/TNFα ratios have been associated with an “anti‐inflammatory state” (e.g., in patients with ARDS or uremia; 26,27)." (PMID 32940965, 2020). "Traditional inflammatory biomarkers, including CRP, TNF-α, and IL-6, have been found to be predictors of cardiovascular disease and even uremia." (PMID 31427482, 2019). "For the proinflammatory cytokine TNF-α, there was a significant difference between the uremia group and the control group in postoperative week 10 (P < 0.05)." (PMID 27493661, 2016). "In the present study, we also demonstrated that the uremia group presented an increased trend over time in the serum cytokines TNF-α, IL-6, and IL-10, and these cytokines were higher than those in the control group at all the investigated time points." (PMID 27493661, 2016). "The serum levels of TNF-α, IL-6, and IL-10 in the uremia group presented an increased trend over time, and these cytokine levels were higher than those in the control group at all the investigated time points." (PMID 27493661, 2016). "The production and release of TNF-α in monocytes further speed up vascular calcification in uremia." (PMID 40689393, 2025). "It is still poorly understood whether high TNF-alpha is one of the reasons or rather one of the effects of uremia." (PMID 36558477, 2022). "Furthermore, we have demonstrated that IL6 plays a key role on HIF activation and TNFα in NFκB activation in uremia." (PMID 33536542, 2021). "One study found that patients with uremia had elevated IL-6, TNF-α, and CRP levels." (PMID 34678995, 2021). "Those who are continuously undergoing high throughput blood purification have decreased serum levels of CRP, interleukin-2, and tumor necrosis factor-α, and high throughput hemodialysis may be beneficial for the prevention of infections in patients with uremia." (PMID 30818331, 2019). "Moreover, these authors have also evaluated the relationships between plasma AOPPs and markers of monocyte activation in uremia and demonstrated a high correlation between AOPPs and renal creatinine clearance and inflammatory cytokine levels such as tumor necrosis factor alpha (TNF-α)." (PMID 26581178, 2015). "The most important is the lack of determination of more serum inflammation (IL-6, IL-10, IL-18, TNF-α), bone metabolic (FGF-23 and bone alkaline phosphatase), and uremia markers." (PMID 36611532, 2022).
uremia (continued). "Our data demonstrate that IL6 and TNFα contribute to the activation of HIF and NFκB respectively in uremia." (PMID 33536542, 2021). "We found in our promoter activation and signaling studies that VEGF production in ECs was induced by TNF-α through AP-1/c-FOS-mediated activation of the VEGF promoter, thus providing new molecular targets for ameliorating uremia-induced inflammation." (PMID 34858433, 2021). "Both cell lines exposed to uremia have also a significant increase in the expression of IL-6, TNFα, and CCL2 without changes in expression of anti-inflammatory cytokines." (PMID 33536542, 2021). "Fat TNF-α over-expression is not inhibited by its high plasma levels and in fact, the levels of sTNFα-R2 are maintained, indicating that fat tissue is an important source of pro-inflammatory cytokines in uremia." (PMID 31191339, 2019).
urticaria (26 papers, 2010 to 2026). A vascular reaction of the skin characterized by erythema and wheal formation due to localized increase of vascular permeability. "The association of IL-13 with TNF α was seen only in urticaria patients." (PMID 20616938, 2010). "These triggers activate innate immunity, CD4 + lymphocytes, and the production of IL-1β, IFN-γ, and TNF-α, which subsequently induce cell damage and apoptosis, which are key mechanisms for the development of angioedema and/or urticaria." (PMID 34906225, 2021). "In patients with different types of urticaria, increased TNF-α activity was detected in skin biopsies." (PMID 30911316, 2019). "However, to achieve long-term relief of urticaria symptoms, continuous treatment with TNF-alpha inhibitors was needed, as intermission led to return of symptoms within a few weeks." (PMID 24167521, 2013). "Microarray analyses have identified IL-6, TNF-α, NF-κB, and TLR-4 as pivotal genes in urticaria pathogenesis." (PMID 40490797, 2025). "Beyond histamine, an immediate release of various factors such as tumor necrosis factor-α (TNF-α), serotonin, proteases, and proteoglycans also occur, manifesting direct or indirect implications in the pathogenesis of urticaria." (PMID 38022623, 2023). "TNF-α has been reported to increase in the lesional and non-lesional skin of patients with cold and pressure urticaria, as well as in the serum of patients with CU, correlating with disease severity." (PMID 35956071, 2022). "Significant correlations were found between concentrations of TNF-α and its receptors, as well as sTNF-R1 and sTNF-R2, but not with the urticaria activity score (UAS)." (PMID 30911316, 2019). "However, it is our present position that the preferred therapy for chronic recalcitrant urticaria not responding to high-dose antihistamines and/or standard immunosuppressive drugs should be omalizumab, and that TNF-alpha inhibitors should be recommended as a second-line therapeutic option." (PMID 24167521, 2013).
Airway obstruction (25 papers, 2007 to 2026). Obstruction of conducting airways of the lung. "The increase in TNF-α production can increase the reactivity of the airway’s smooth muscles, thereby aggravating airway obstruction and causing wheezing." (PMID 35854266, 2022). "Previous data in the field of RSV has suggested that a downregulation in pro-inflammatory cytokines, such as TNF-α corresponds with significantly improved clinical disease (i.e., bodyweight loss, illness score, airway obstruction)." (PMID 31398832, 2019). "In contrast, the Th1-associated cytokine TNF-α was necessary to mediate airway obstruction and weight loss." (PMID 25769044, 2015). "Specifically, the Th2-biased immune response mediates AHR and mucus hypersecretion while TNF-α contributes to both airway obstruction and weight loss." (PMID 25769044, 2015). "In contrast, neutralization of TNF-α in FI-RSV-immunized mice significantly (p<0.05) reduced both the increase in airway obstruction and weight loss following RSV infection." (PMID 25769044, 2015). "In contrast, the Th1-associated cytokine TNF-α was found to be critical for the induction of airway obstruction and weight loss associated with FI-RSV VED." (PMID 25769044, 2015). "However, the neutralization of TNF-α led to a significant reduction in both airway obstruction and weight loss in FI-RSV-immunized mice." (PMID 25769044, 2015). "This is in line with other studies having shown that vaccine-induced circulating TNFα-producing CD4+ and CD8+ T-cells mediate weight loss, pulmonary dysfunction and airway obstruction upon RSV infection." (PMID 39472590, 2024). "Recently, increased serum TNF-α level has been also correlated to the severity of airway obstruction among COPD patients." (PMID 30155241, 2018). "This same study also described TGF-β1 as being a modulator of atopy, and both TGF-β1 and TNF-α were found to be elements that modulate clinical severity and airway obstruction in an additive manner." (PMID 25759826, 2014). "Among these, IL-1β can trigger PTGS2 to induce MUC5AC mucin expression through ERK or p38 MAPK, exacerbating airway obstruction, whereas TNF-α may induce PTGS2 to produce prostaglandin E2 (PGE2) and other substances, exacerbating airway inflammation." (PMID 41557720, 2026). "TNF-α enhances the expression of IL-like inflammatory factors through Akt and JNK signaling, promoting the occurrence of airway inflammatory disease and causing damage to airway epithelial cells, ultimately leading to airway obstruction in children." (PMID 41200114, 2025). "Even though TNF-α is a pro-inflammatory cytokine in nature, which could enhance pulmonary inflammation and airway obstruction, the local and balanced secretion of TNF-α by AMs proves to be beneficial during hRSV infection, probably because of the promotion of an antiviral local state." (PMID 32545470, 2020). "Additionally, tumor necrosis factor-alpha (TNF-α) released by neutrophils upregulates the expression of epidermal growth factor receptors on airway epithelial goblet cell, resulting in mucus hypersecretion thereby further exacerbating airway obstruction." (PMID 31281845, 2019). "For instance, tumor necrosis factor-alpha (TNF-α) and interleukin-10 (IL-10) represent pro- and anti-inflammatory cytokines, respectively, and polymorphisms in TNF-α and IL-10 have been associated with obstructive lung disease, a complex disease characterized by airway obstruction and inflammation." (PMID 20459696, 2010). "In contrast, the neutralization of TNF-α led to the significant reduction in airway obstruction and no alteration to AHR." (PMID 25769044, 2015). "In our previous studies, palivizumab administration did not modify BAL concentrations of TNF-α nor the initial peak of airway obstruction (AO) observed in this model." (PMID 17961258, 2007).
anterior uveitis (25 papers, 2010 to 2026). Inflammation of the iris and anterior chamber of the eye. "The current study demonstrates that IL-4, IL-6, IL-18, and TNFα have the potential to be relevant in dogs with post-phaco anterior uveitis." (PMID 35998207, 2022). "The proinflammatory cytokine TNF-α in the aqueous humor plays an important role in the pathogenesis of anterior uveitis." (PMID 34356327, 2021). "TNF-α levels are significantly elevated in the aqueous humor in the early stages of endotoxin-induced anterior uveitis." (PMID 34356327, 2021). "Many candidate-gene association studies have reported nominal SNP associations in interleukin (IL) genes, tumor necrosis factor (TNF) genes, and complement factors correlated with anterior uveitis." (PMID 32492107, 2020). "Several observational studies and one meta-analysis showed that the soluble TNF receptor fusion protein (ETA) is less effective in preventing anterior uveitis, compared to the anti-TNFα monoclonal antibodies (IFX and ADA)." (PMID 32231384, 2020). "Patients taking anti-TNF-α agents exhibited significantly reduced rates of recurrence of anterior uveitis in the major trials, with stronger protection afforded by infliximab and adalimumab." (PMID 22229035, 2012). "Our findings in the drug-switching population also carry practical implications, suggesting a consideration for transitioning from etanercept to anti-TNFα monoclonal antibodies as a potential treatment strategy for recurrent anterior uveitis in patients with AS." (PMID 38337605, 2024). "In humans with anterior uveitis, specific pro-inflammatory cytokines have been detected in aqueous humor (AH) including Interleukin (IL)-6, IL-8, IL-10, IL-13, IL-17, interferon-gamma (IFNγ), and tumor necrosis factor-alpha (TNFα)." (PMID 35998207, 2022). "Also, IL-4, IL-6, IL-18, and TNFα may be important pro-inflammatory cytokines in dogs with anterior uveitis and POH following phacoemulsification (‘POH group’)." (PMID 35998207, 2022). "Recent studies suggest that certain antioxidant and anti-inflammatory agents can reduce the severity of anterior uveitis by modulating HIF-1α and TNF-α signaling pathways." (PMID 41402737, 2025). "Dogs with anterior uveitis and POH following phacoemulsification surgery express elevated levels of IL-4, IL-6, IL-18 and TNFα in AH, which is consistent with the human literature." (PMID 35998207, 2022). "Tumor necrosis factor-alpha (TNF-α) is a pro-inflammatory cytokine, the levels of which are significantly elevated in the aqueous humor during allograft rejection and anterior uveitis." (PMID 20824160, 2010). "The likely different response rates to biological therapy between non-infectious pediatric anterior uveitis of different aetiologies, as well as treated with anti- TNF-α agents, infliximab or adalimumab, have been described in the literature." (PMID 34669094, 2022).